ATXN1 (ataxin 1)
Diseases named in the same sentence as ATXN1 in open-access papers (continued):
Sharing a sentence is not in itself a finding about the gene and the disease.
CNS sarcoma (2 papers, 2022 to 2025). "Because SARC‐CIC may present non‐CIC fusions, we suggest CNS sarcoma, CIC/ATXN1 complex‐fused, as a closer consensual nosological term for this group of tumors." (PMID 39442927, 2025).
experimental autoimmune encephalomyelitis (2 papers, 2021 to 2025). An autoimmune demyelinating disease of the central nervous system that is produced experimentally in animals by the injection of homogenized brain or spinal cord in Freund's adjuvant. "We have recently shown that ATXN1 exerts a protective immunomodulatory activity in the MS model experimental autoimmune encephalomyelitis (EAE)." (PMID 33478569, 2021). "We employ the experimental autoimmune encephalomyelitis (EAE) mouse model, to further explore the role of ATXN1 in MS pathogenesis." (PMID 40321775, 2025). "To examine the role of ATXN1 in EAE, we immunized 8-week-old WT, f-ATXN1146Q/2Q, and Atxn12Q/− female mice, with myelin oligodendrocyte glycoprotein (MOG) peptide 35 to 55 (MOG35–55) to induce experimental autoimmune encephalomyelitis (EAE)." (PMID 40321775, 2025).
gastric cancer (2 papers, 2022). A primary or metastatic malignant neoplasm involving the stomach. "Hmgb1/2 inhibits genotoxic stress in polyglutamine diseases by interacting with mutant ataxin-1 and huntingtin protein; suppressing Hmgb2 expression causes gastric cancer cells to be less sensitive to chemotherapy." (PMID 35574435, 2022).
Obesity (2 papers, 2013 to 2025). Accumulation of substantial excess body fat. "Here we report a 6p deletion of about 1 Mb encompassing five genes (ATXN1, DTNBP1, JARID2, MYLIP and GMPR), identified in a patient with severe ID, hypotonia, brain anomalies, EEG abnormalities, macrosomia, obesity, and ASDs with associated hyperactivity and behavioral abnormalities." (PMID 23324214, 2013).
-Aldrich syndrome (1 paper, 2023). "We found 14 common targets for this highlighted anxiogenic miRs, among them Solute carrier family 17 (vesicular glutamate transporter), member 6 (Slc17a6), Wiskott-Aldrich syndrome-like (Wasl), and Ataxin-1 (Atxn1) have a higher rank for interaction." (PMID 36979479, 2023).
adult T-cell leukemia/lymphoma (1 paper, 2024). A peripheral (mature) T-cell neoplasm linked to the human T-cell leukemia virus type 1 (HTLV-1), adult T-cell leukemia/lymphoma is endemic in several regions of the world, in particular Japan, the Caribbean, and parts of Central Africa. "ATXN1 or CIC alterations are present in 53% of adult T-cell leukemia/lymphoma (ATLL) cases, and CCR4 (C–C chemokine receptor 4) mutations are common, and the majority of ATLL patients exhibit CCR4 overexpression, which is associated with skin involvement and worse prognosis." (PMID 38178117, 2024).
asthma (1 paper, 2015). "Three of the predicted target genes, namely ATXN1, NR3C1 and PTEN, have previously been associated with asthma." (PMID 26693910, 2015). "The remaining 4 target genes were assessed based on previous literature: ATXN1 has been associated with asthma, NFAT5 is implicated in the regulation of proinflammatory cytokines, NR3C1 is a target for steroid-based asthma treatments and TAB2 is a validated miR-155-5p target." (PMID 26693910, 2015).
Autoimmunity (1 paper, 2024). The occurrence of an immune reaction against the organism's own cells or tissues. "CIC forms a transcriptional repressor complex with the protein ataxin 1 (ATXN1), involving in brain development and autoimmunity regulation, implicating in neurodegenerative diseases." (PMID 38315329, 2024).
brain cancer (1 paper, 2017). A primary or metastatic malignant neoplasm affecting the brain. "Analysis on the expression profiles of ATXN1 in various cancer samples using the Oncomine database analysis tool reveals that the level of ATXN1 is significantly downregulated in breast and brain cancer patients." (PMID 28212558, 2017).
cerebellar degeneration (1 paper, 2013). Degeneration of the cerebellum. "The HAT, Tip60 has been reported to interact with ataxin 1 protein in Spinocerebellar ataxia 1 (SCA1) mouse model and contribute to cerebellar degeneration associated with SCA1, a neurodegenerative disease caused by polyglutamine tract expansion in the ataxin-1 protein." (PMID 23543406, 2013).
cervical tumors (1 paper, 2017). "We performed immunohistochemical analysis to determine the expression patterns of ATXN1 and pERK1/2 in tissues and human cervical tumors." (PMID 29212253, 2017). "Results from a tumor tissue microarray analysis revealed that the ATXN1 expression level was highly elevated in cervical tumor specimens." (PMID 29212253, 2017).
childhood cancer (1 paper, 2023). "Of note, rs34533789 (within the intron of ATXN1), which has been reported to be associated with radiation-induced hearing loss for childhood cancer survivors, was replicated in our study (HR = 1.35, P value = 0.04)." (PMID 37062025, 2023).
colorectal cancer (1 paper, 2021). A primary or metastatic malignant neoplasm that affects the colon or rectum. "In colorectal cancer, it has been reported that ATXN1 is a putative cancer gene and expression of ATXN1 in tumor cells is downregulated compared with normal colon cells." (PMID 34638401, 2021).
congenital heart disease (1 paper, 2020). A heart disease that is present at birth. "As a second example, a cardiac-specific enhancer in the final intron of ATXN1 on chromosome 6 contained a DNM from the DDD cohort associated with congenital heart disease." (PMID 32764605, 2020).
dominant retinitis pigmentosa (1 paper, 2016). "Of which, three variants (ATXN1:NM_000332:p.E357K, TCF4:NM_001243226:c.1793-5G > A and KRT3:NM_057088:c.1189-5T > C) are known pathogenic variants of dominant retinitis pigmentosa." (PMID 27391953, 2016).
dyslipidemia (1 paper, 2022). "miR-6769-5p is another intestinal EV microRNA found relevant to dyslipidemia. miR-6769-5p was found in the EVs collected from the Caco-2 cell culture medium, and was upregulated by carnosine treatment, which could enhance neurite growth via suppression of its target gene, ataxin 1 (Atxn1)." (PMID 36360201, 2022).
leukaemia (1 paper, 2007). "One property of pathogenic ataxin-1 protein is to sequester and disrupt specific nucleoproteins such as promyelocytic leukaemia nuclear domains (PML-NDs)." (PMID 17925862, 2007).
lung carcinoma (1 paper, 2014). "Moreover, HOTAIR-mediated ubiquitination and degradation of Ataxin-1 is of particular interest to lung cancer because Ataxin-1 is essential to lung alveolization." (PMID 25491133, 2014).
neuropathy (1 paper, 2021). A disorder affecting the nervous system that manifests with pain, tingling, numbness, and/or muscle weakness. "In spinocerebellar ataxia type 1 (SCA1), gain-of-function in the mutant ATXN1 contributes to SCA1’s neuropathy." (PMID 34768779, 2021).
olivopontocerebellar atrophy (1 paper, 2020). A group of sporadic and inherited neurodegenerative disorders affecting the cerebellum, pons, and inferior olives. "Although wild type ATXN1 is widely expressed, mutant ATXN1 (mATXN1) causes olivopontocerebellar atrophy with selective degeneration of Purkinje cells and neurons in the deep cerebellar nuclei, the brainstem and the spinal cord." (PMID 32581696, 2020).
optic atrophy (1 paper, 2020). A disorder characterized by loss of optic nerve fibers. "Alternatively, development of maculopathy may be independent of optic atrophy in SCA‐ATXN1, which may be attributed to cell‐specific transcriptional effects of expanded ATXN1." (PMID 32626794, 2020).
preeclampsia (1 paper, 2018). Preeclampsia is a hypertensive disorder of pregnancy that is characterized by new-onset hypertension with proteinuria presenting after 20 weeks of gestation, and depending on mild or severe forms may initially present with severe headache, visual disturbances, and hyperreflexia. "The variants in the SI and ATXN1 genes demonstrated in the present study are of more dubious clinical relevance for preeclampsia." (PMID 29758065, 2018).
progressive ataxia (1 paper, 2019). "Expansion of CAG repeats within the ATXN1 gene encoded the cytosol/nuclear protein ataxin-1 (Atxn1) causes the adult-onset neurodegenerative disease SCA1 characterized by progressive ataxia, oculomotor deficits, pyramidal/extrapyramidal signs." (PMID 31892274, 2019).
proteinopathies (1 paper, 2015). "Rather, we suggest ATXN1 propagates through a secretion and reuptake mechanism between neighboring cells as has been proposed for other proteinopathies." (PMID 26673892, 2015).
soft tissue sarcoma (1 paper, 2023). A malignant neoplasm arising from muscle tissue, adipose tissue, blood vessels, fibrous tissue, or other supportive tissues excluding the bones. "These new “CIC fused” (CIC‐fused/ATXN1::NUTM1) and “BCOR rearranged” (BCOR fused/ITD/ YWHAE) soft tissue sarcomas (STS) are not well described." (PMID 37212486, 2023).
spastic ataxia (1 paper, 2023). "In an African ancestry case with spastic ataxia and without a family history, a heterozygous ATXN1 trinucleotide expansion was detected to designate SCA1." (PMID 37712079, 2023).
neurodegenerative disease (49 papers, 2010 to 2026). A disorder of the central nervous system characterized by gradual and progressive loss of neural tissue and neurologic function. "SCA1 is a severe neurodegenerative disease caused by CAG-trinucleotide repeat expansions (> 39) in the ATXN1 gene." (PMID 40029919, 2025). "A mutant form of the ataxin-1 protein with an expanded polyglutamine (polyQ) tract is the underlying cause of the inherited neurodegenerative disease spinocerebellar ataxia 1 (SCA1)." (PMID 32005838, 2020). "SCA1 is a dominantly inherited neurodegenerative disease caused by repeated expansions of Poly Q in ataxin-1." (PMID 31275113, 2019). "An expansion of the polyQ tract of ATXN1 has been identified as the cause of the neurodegenerative disease SCA1." (PMID 31655597, 2019). "In addition to SCA1, ataxin-1 is also implicated in other neurodegenerative diseases." (PMID 36187346, 2022). "As shown by the program results DE miR-3687, miR-612, miR-4261, miR-504-3p, miR-126-5p,and miR-411-5p bind to the mRNA of the B3GNT2, CSMD2, ATN1, CREBBP, ATXN1, EMIN4, and EFNA5 genes, which are associated with neurodegenerative diseases." (PMID 39049823, 2024). "They discovered that ATXN1 interacts with multiple factors to drive SCA1, revealing the mechanistic complexity that underlies regional vulnerability in neurodegenerative diseases." (PMID 36577402, 2023). "For example, neurodegenerative disease-related protein aggregates, such as polyglutamine, huntingtin, ataxin-1, and superoxide dismutase-1, block clathrin-mediated endocytosis and intracellular trafficking in neurodegenerative disease." (PMID 30866990, 2019). "In mammals, CIC was identified as an interacting protein of ATXN1, the causative protein of SCA1 neurodegenerative disease." (PMID 26124181, 2015). "Several lines of experimental evidence indicate that long polyQ tracts in neurodegenerative disease proteins such as ATXN1 have to undergo a conformational change before they can assemble into insoluble protein aggregates." (PMID 22916034, 2012). "ATXN1 (ataxin 1) is involved in the development of neurodegenerative diseases." (PMID 32600379, 2020). "The polyQ-ataxin-1 phase transition model that we propose will thus provide a framework for ongoing investigations to contribute new knowledge to a mechanistic understanding how polyQ-ataxin-1 can drive the pathological changes observed in the neurodegenerative disease SCA1." (PMID 32005838, 2020). "We also present the complete list of human proteins with PrLDs and discuss the prevalence of the PrLD in nucleic-acid binding proteins that are often connected to neurodegenerative disease, including: ataxin 1, ataxin 2, FUS, TDP-43, TAF15, EWSR1, hnRNPA1, and hnRNPA2." (PMID 26996412, 2016). "To assay expression of the Drosophila Lipocalins in a poly-Q-based neurodegenerative disease, we have used the GAL4/UAS system to express a pathogenic version of human Ataxin 1 with an expanded glutamine tract (hATXN182Q) in Drosophila retinal photoreceptors using the gmr:GAL4 driver." (PMID 25888134, 2015). "ATXN1 is the cause of spino-cerebellar ataxia type 1 (SCA1, OMIM:164400), a dominantly inherited neurodegenerative disease, through CAG repeat expansion with a gain-of-function mechanism, while loss-of-function of ATXN1 seems to lead to motor coordination impairments and learning deficits." (PMID 23324214, 2013). "A further dissection of the effect of these direct and indirect pathways on suppressing mutant ataxin-1 and AR toxicity could provide critical insights into the role of Nlk in neurodegenerative diseases and whether there is a unifying protective effect of Nlk reduction." (PMID 37384409, 2023). "It has been suggested a link between CAG repeat number in the HTT, ATXN1 and ATXN2 genes and different neurodegenerative diseases." (PMID 39974178, 2025). "It thus seems unlikely that ATXN1 oligomers propagate transsynaptically in SCA1, as has been suggested with other neurodegenerative diseases." (PMID 26673892, 2015).
neurodegenerative disease (continued). "Several miRNAs have been shown to target different neurodegenerative disease-related proteins and modulate their concentration in cells (e.g., BACE1, ataxin-1 or α-synuclein in the case of Alzheimer’s disease (AD), SCA1 and Parkinson’s disease (PD), respectively (and references therein))." (PMID 26331031, 2014).
cancer (20 papers, 2010 to 2025). A tumor composed of atypical neoplastic, often pleomorphic cells that invade other tissues. "We found that CAG repeat number variations in the long ATXN1 gene were associated with the risk of cancer, an important relationship from both biological and clinical point of view." (PMID 39974178, 2025). "ATXN1, encoding a chromatin-bindingprotein, exhibited time-dependent functions in cancer development, promoting mitosisduring early tumorigenesis and enhancing invasion during hypoxic tumor growth." (PMID 39116405, 2024). "However, the cancer risk model demonstrated only a marginal association with the ATXN1 gene, suggesting a minimal effect size that warrants cautious interpretation and limited use as an independent predictor." (PMID 39974178, 2025). "The long CAG ATXN1 allele gene was associated with the risk of cancer." (PMID 39974178, 2025). "ATXN1 loss-of-function is implicated in cancer pathogenesis." (PMID 34638401, 2021). "In this study, we investigated the effect of HTT, ATXN1 and ATXN2 CAG allele sizes in the risk of developing the disease and cancer comorbidity in a large cohort of patients with iPD." (PMID 39974178, 2025). "Studies have shown that changes in ATXN1 expression can affect cell growth processes critical to cancer development." (PMID 39202384, 2024). "The seven hub RBPs CD3EAP, POP5, NOP10, ATXN1, ZC3H12C, RBPMS, and SBDS were implicated in the progression and prognosis of many cancers." (PMID 36262474, 2022). "In the present study, we discovered a novel mechanism through which ATXN1 regulates the epithelial–mesenchymal transition (EMT) of cancer cells." (PMID 28212558, 2017). "Previously, we discovered a novel mechanism through which ATXN1 regulates the epithelial–mesenchymal transition of cancer cells." (PMID 29212253, 2017). "Thus, it is suggested that ATXN1 expressed in cancer cells protects the cells from EMT and subsequent malignant progression." (PMID 34638401, 2021). "A potential link between ATXN1 expression (both upregulation and downregulation) and cancer development in humans has been suggested; however, it remains unknown whether ATXN1 acts as a tumor suppressor or an oncogene." (PMID 28212558, 2017). "Metastatic cancer cells survive under normoxia, which increases ATXN1 levels." (PMID 29212253, 2017). "Although some of these genes can easily be linked with cancer biology (e.g. ATXN1 and PLXNC1), for others no such association has been reported (e.g. APOB)." (PMID 27014907, 2016). "Therefore, regulation of ATXN1 expression may serve as a potential therapeutic target in other cancers." (PMID 28212558, 2017). "Considering this, we hypothesized that ATXN1 is involved in EGF-mediated cancer growth." (PMID 29212253, 2017). "PLC/PRF5 cells transfected with ataxin-1 siRNA showed a significantly higher IC50, higher migration/invasion capability, higher cancer stem cell population, and an EMT phenotype." (PMID 34638401, 2021). "We also revealed that miR-125-5p suppressed ataxin-1 as a target gene and consequently induced Snail-mediated epithelial-mesenchymal transition (EMT) and cancer stemness." (PMID 34638401, 2021). "In addition, in OSCC cell lines, hsa_circ_0008309 may exert an anti-cancer effect by manipulating the hsa_circ_0008309-miR-382-5p/miR-136-5p-ATXN1 pathway, and hsa_circ_0008309 overexpression inhibited miR-382-5p and miR-382-5p expression and increased ATXN1 expression." (PMID 32213977, 2020). "Despite lacking experimental validation, ATXN1 andCDC42EP1 are postulated as cancer driver genes in a subset ofOTSCC." (PMID 39116405, 2024).
cancer (continued). "The rest four genes (YWHAG, ATXN1, UBQLN4, and SMAD9) also ranked high because of its high degree in transition probability W. Although they are not presented in CGC, some evidences show that these four candidate genes have functional roles in cancer or cancer-related biological processes." (PMID 31888623, 2019). "Although ATXN1, SMAD9, UBQLN4 and GRB2 are not included in CGC, we have already mentioned that ATXN1, SMAD9 and UBQLN4 are all relate to cancers or pathway in the last paragraph." (PMID 31888623, 2019).